PABPC1L2A (poly(A) binding protein cytoplasmic 1 like 2A)
Synonyms: RBM32A
Gene: Protein-coding gene on chromosome X (73,077,276 to 73,079,512, reverse strand). Ensembl gene ENSG00000186288.
Gene Ontology:
Molecular function: mRNA 3'-UTR binding; poly(U) RNA binding; nucleic acid binding; poly(A) binding; RNA binding
Cellular component: extracellular exosome; cytoplasmic stress granule; cytosol; nucleus; ribonucleoprotein complex
Homologues: Orthologues: macaque PABPC1L2A (100% identical), dog PABPC1L2A (99% identical), mouse Pabpc1l2a (94% identical), mouse Pabpc1l2b (94% identical), rat Pabpc1l2a (93% identical), zebrafish pabpc1a (78% identical), zebrafish pabpc1b (78% identical). Paralogues in human: PABPC1L2B (100% identical), PABPC1 (80% identical), PABPC4 (76% identical), PABPC3 (72% identical), PABPC1L (70% identical), PABPC4L (62% identical), PABPC5 (58% identical), TARDBP (23% identical), SYNCRIP (22% identical), RBMS1 (19% identical), HNRNPR (18% identical), RBM34 (18% identical), and 12 more.